LEP (leptin)
Diseases named in the same sentence as LEP in open-access papers (continued):
Sharing a sentence is not in itself a finding about the gene and the disease.
ovarian tumors (5 papers, 2009 to 2023). "Interestingly, reports revealed that the serum leptin levels were suppressed in ovarian tumour-associated hyperandrogenism (i.e., excess levels of androgens like testosterone)." (PMID 30510663, 2018). "In addition, the data of this study suggested that HFD increased leptin to stimulate ovarian tumour growth in vivo." (PMID 30510663, 2018). "Several ovarian biomarkers, such as Kallikreins, osteopontin, leptin, HE-4, LPA, MUC1 and SLPI, have been identified in the past several years through various approaches, including gene expression profiling and proteomics analysis of ovarian tumors." (PMID 19619303, 2009).
protein-energy malnutrition (5 papers, 2013 to 2025). A nutritional deficit that is caused by inadequate protein or calorie intake. "Neonatal leptin is positively associated with birthweight and being large for gestational age, and leptin in infancy is negatively associated with protein-energy malnutrition." (PMID 40707829, 2025). "On the other hand, Protein energy malnutrition decreases leptin concentrations and increases serum levels of the stress hormone glucocorticoid." (PMID 37127636, 2023). "The adipocyte-derived proteins, adiponectin and leptin, with opposite inflammatory and atherogenic effects, are involved in protein-energy malnutrition and in the development of atherosclerotic CVD in CKD patients." (PMID 31316299, 2019). "Protein-energy malnutrition reduces leptin concentrations which impairs macrophage functions, ability to engulf pathogens and to produce proinflammatory cytokines." (PMID 30534129, 2018). "Recent epidemiologic studies have shown that increased serum value of leptin may reduce nutrient intake and contribute to the development of protein-energy malnutrition that may be shown by low levels of serum cholestrol." (PMID 28197438, 2013).
sarcoidosis (5 papers, 2010 to 2024). Sarcoidosis is a multisystemic disorder of unknown cause characterized by the formation of immune granulomas in involved organs. "Leptin, a pro-inflammatory adipokine, shows potent immunomodulatory effects; these potentially contribute to autoimmunity and increase the risk of sarcoidosis." (PMID 38611622, 2024). "Therefore, we confirmed the upregulation of serum leptin in sarcoidosis patients, which suggests that leptin may be a novel diagnostic marker." (PMID 26368286, 2015). "The precise mechanism linking obesity to sarcoidosis remains unclear, but excessive leptin secretion from adipocytes in obese patients is proposed as a possible explanation." (PMID 38611622, 2024). "Thus, our results identified elevated expression of ICAM-1 and leptin in serum and granulomas of sarcoidosis patients." (PMID 26368286, 2015).
systemic sclerosis (5 papers, 2010 to 2020). A chronic disorder, possibly autoimmune, marked by excessive production of collagen which results in hardening and thickening of body tissues. "More recently, another study which enrolled 100 patients with confirmed systemic sclerosis diagnosis and 20 healthy individuals revealed that the patients presented significantly elevated serum levels of leptin." (PMID 33597945, 2020). "Several meta-analyses showed that in patients suffering from systemic sclerosis (SSc) leptin levels were comparable to those of the healthy population." (PMID 33008429, 2020). "Several meta-analyses showed that in patients suffering from systemic sclerosis, serum leptin levels were comparable to those of healthy control individuals." (PMID 33597945, 2020). "Previous studies have indicated that serum TNF-α levels were positively correlated with leptin levels in patients with systemic sclerosis." (PMID 32265847, 2020). "The aim of this study was to investigate the serum concentration of metabolic adipose tissue factors: adiponectin, resistin, leptin and endothelial proteins: endothelin-1, fractalkine and galectin-3 in patients with systemic sclerosis." (PMID 31667578, 2020). "On the contrary, several studies showed that the serum levels of leptin increased in patients with systemic sclerosis." (PMID 33597945, 2020). "The underlying mechanism whereby leptin facilitates the development of systemic sclerosis could be also attributed to the function of leptin in indirectly stimulating the development of fibrosis." (PMID 33597945, 2020). "Nevertheless, the serum leptin levels were significantly reduced in patients with active systemic sclerosis, suggesting that leptin could be used as an activity biomarker in patients with this disease." (PMID 33597945, 2020). "Accordingly, leptin might be useful as a potential marker of vascular damage in systemic sclerosis." (PMID 33597945, 2020). "Thus, it seems that serum levels of leptin are not significantly different between patients with systemic sclerosis and healthy individuals." (PMID 33597945, 2020).
thyroid nodule (5 papers, 2015 to 2023). A small circumscribed mass in the THYROID GLAND that can be of neoplastic growth or non-neoplastic abnormality. "Elevated serum leptin concentrations in obese individuals can promote increased thyroid-stimulating hormone levels, leading to the occurrence and development of thyroid nodules." (PMID 37152970, 2023). "Leptin plays a vital role in forming thyroid nodules and cancer through several mechanisms." (PMID 37374075, 2023). "We found that the thyroid nodule group manifested similar BMI as compared to the control groups; thus, the leptin might not vary in the two groups." (PMID 29158735, 2017).
vascular dementia (5 papers, 2011 to 2025). A degenerative vascular disorder affecting the brain. "The consequence is that people with overweight and increased leptin status are more exposed to vascular dementia than the others." (PMID 30893833, 2019). "Similarly, a study in adult patients with a mean age of 60 years with AD or vascular dementia showed serum leptin levels comparable to those of healthy controls and individuals with subjective memory complaints." (PMID 41516046, 2025). "Once again this demonstrated a link between low leptin levels and the development of AD when compared to nondemented or vascular dementia patients." (PMID 22013440, 2011).
visceral leishmaniasis (5 papers, 2016 to 2020). A severe form of leishmaniasis characterized by irregular bouts of fever, substantial weight loss, swelling of the spleen and liver, and anemia (which may be serious). "Moreover, an impaired leptin signaling is linked to a reduction of the innate immune response to Leishmania, and low levels of leptin have been associated with severity parameters in visceral leishmaniasis patients." (PMID 33316927, 2020). "Visceral leishmaniasis (VL) is responsible for several deaths in malnourished children accompanied by diminished circulating leptin and impaired cell-mediated immunity." (PMID 29116252, 2017). "Leptin may have a role in modulation and restoration of effective responses against visceral leishmaniasis." (PMID 32309235, 2020).
astrocytoma (4 papers, 2012 to 2023). "The MAPK/ERK1/2 pathway is one of the three canonical pathways triggered by leptin, which is associated with the leptin-mediated growth and metastasis of various epithelial-derived cancers and NC-derived astrocytoma." (PMID 37895840, 2023). "This study illustrates key signaling molecules involved in leptin-induced proliferation and migration of human astrocytoma cells, and demonstrates a cross-talk between leptin and the inflammatory sPLA2-IIA." (PMID 28249041, 2017). "Alike in 1321N1 astrocytoma cells, a synergistic effect on cell growth was found when astrocytes were stimulated with a suboptimal dose of leptin in combination with a suboptimal dose of sPLA2-IIA." (PMID 28249041, 2017). "Leptin enhances sPLA2-IIA-mediated effects in 1321N1 astrocytoma cells, and sPLA2-IIA enhances leptin capacity to signal by inducing overexpression of its receptor, thereby possibly contributing to a more aggressive behaviour of the basal tumor phenotype." (PMID 28249041, 2017). "Next, to investigate whether the activation of Src/ERK/Akt/mTOR kinases were key elements of the leptin induced proliferation in 1321N1 astrocytoma cells, they were incubated in the absence or presence of an optimal concentration of human recombinant leptin (0.5 μM) at different times." (PMID 28249041, 2017). "We observed that leptin increases the proliferative and migratory effects of sPLA2-IIA on both astrocytoma cells and primary astrocytes." (PMID 28249041, 2017). "Leptin, at concentrations with minimal or no activating effects on astrocytoma cells, enhanced growth and migration promoted by low doses of sPLA2-IIA." (PMID 28249041, 2017). "This study characterizes the link between leptin and sPLA2-IIA on 1321N1 astrocytoma cells." (PMID 28249041, 2017). "Interestingly, although in some cell types leptin signaling is dependent on EGFR transactivation, in 1321N1 astrocytoma cells the presence of the specific EGFR inhibitor, AG1478, does not abrogate the mitogenic effects induced by leptin alone." (PMID 28249041, 2017).
Azoospermia (4 papers, 2018 to 2024). Absence of any measurable level of sperm,whereby spermatozoa cannot be observed even after centrifugation of the semen pellet. "This may explain why low levels of leptin treatment were able to increase LSC differentiation and testosterone levels in cells extracted from the testis biopsies of azoospermia men in our study." (PMID 35246515, 2022). "It is probable that measuring leptin and FSH levels is a sensitive biomarker in predicting the successful retrieval of sperm in obese adult males with non-obstructive azoospermia." (PMID 38203349, 2023).
bacterial pneumonia (4 papers, 2011 to 2021). Acute infection of the lung parenchyma caused by bacteria (e.g., Streptococcus pneumoniae, Haemophilus influenzae, Chlamydia pneumoniae, Mycoplasma pneumoniae, and Legionella pneumophila). "Leptin-deficient mice have an impaired resistance to Gram-negative pneumonia and listeria monocytogenes and enhanced sensitivity to endotoxin-induced lethality." (PMID 30618812, 2018). "This increased susceptibility to bacterial pneumonia in the leptin-deficient mice was associated with reduced alveolar macrophage phagocytosis of K. pneumoniae in vitro; importantly, in vitro alveolar macrophage phagocytosis function was restored by the addition of exogenous leptin." (PMID 21695035, 2011). "As expected, normal mice displayed increased blood and lung leptin levels in response to bacterial pneumonia." (PMID 21695035, 2011). "Also, Leptin can augment IFN-γ synthesis during the course of bacterial pneumonia, which could enhance macrophage effector function." (PMID 21695035, 2011). "Therefore, leptin plays an important role in host defense against bacterial pneumonia." (PMID 21695035, 2011).
beta thalassemia (4 papers, 2012 to 2015). Beta-thalassemia (BT) is characterized by deficiency (Beta+) or absence (Beta0) of synthesis of the beta globin chains of hemoglobin (Hb). "The aim of this study was to evaluate leptin serum levels in patients with major beta thalassemia which was also associated with their ferritin serum levels." (PMID 24575271, 2013). "Our results showed that leptin serum level was significantly higher for ages older than 10 and this issued fact introducing leptin as a biomarker for evaluating cardiac involvement in patients with major beta thalassemia." (PMID 25914798, 2015). "The purpose of this study is to evaluate the relationship between leptin and troponin serum levels with cardiac involvement in patients with major beta thalassemia." (PMID 25914798, 2015). "This study aimed to assess the relationship between levels of leptin and troponin serums in patients with major Beta thalassemia." (PMID 25914798, 2015). "In this study which was conducted to evaluate leptin in patients with beta-thalassemia, serum leptin levels in patients with thalassemia was significantly lower than normal participants." (PMID 24575271, 2013). "In this study, a significant difference was found between the serum leptin level and thyroxin (T4) level in children with major beta thalassemia (P value=0.05)." (PMID 24575288, 2013). "The purpose of this study was to investigate the relationship between serum leptin level and thyroid hormones in children with major beta-thalassemia." (PMID 24575288, 2013). "In this study which was conducted to evaluate leptin in patients with beta-thalassemia, serum leptin levels were significantly lower than normal participants." (PMID 24575271, 2013). "In patients with major beta thalassemia, there was a significant correlation between leptin serum level and thyroxin hormone." (PMID 24575288, 2013). "This study was designed to investigate the relationship between leptin serum level and thyroid hormones in children with major beta-thalassemia." (PMID 24575288, 2013). "Beta-thalassemia is the most common hematology disease in human and leptin is one of the hormone that produce by adiposities cells." (PMID 24575288, 2013). "Due to the effectiveness of leptin on vascular inflammation, high levels of leptin correlate with the increased endothelial inflammatory response in beta-thalassemia." (PMID 24575271, 2013). "Since Leptin increases with the advent of cardiac involvement and independent from troponin T, it can be a predictive marker of cardiac involvement in patients with major beta thalassemia." (PMID 25914798, 2015). "According to the results of the present study, leptin may be used in children with major thalassemia as a selected Cardiac marker involvement screening." (PMID 25914798, 2015). "Also there was a significant correlation between leptin serum level and BMI in patients with major beta thalassemia." (PMID 24575288, 2013). "In addition, a significant correlation was between the leptin serum level and body mass index (BMI) in patients with major beta thalassemia (P value=0.008)." (PMID 24575288, 2013). "In hemolytic anemia such as major beta-thalassemia, this defect in the hematopoietic cells may lead to reduced levels of leptin in these patients." (PMID 24575271, 2013). "Based on the results of this study, major thalassemia reduces serum levels of leptin regardless of age and body mass." (PMID 24575271, 2013). "In this study, there was not significant correlation between leptin serum level and thyroid-stimulating hormone in patients with major beta thalassemia." (PMID 24575288, 2013).
bladder cancer (4 papers, 2015 to 2021). "In bladder cancer, a multivariate analysis revealed a higher risk of progression (HR = 5.148, 95% CI = 1.190–22.273; p = 0.028) in patients with leptin-positive muscle-invasive tumors." (PMID 33799880, 2021). "Fei Mao et al41 identified that Leptin G19A polymorphism was related with a decreased risk of bladder cancer in Chinese Han people, which implied that the mutation of various genes was associated with the occurrence and development of bladder cancer." (PMID 33780049, 2021). "An immunohistochemistry study using a tissue microarray of bladder cancer showed that strong leptin expression tended to be present more often in tumors than in benign tissues." (PMID 33799880, 2021).
brain infarction (4 papers, 2021 to 2025). Tissue necrosis in any area of the brain, including the cerebral hemispheres, the cerebellum, and the brain stem. "At baseline, leptin levels were significantly associated with the presence of brain infarcts." (PMID 38686200, 2024). "The results of the present research suggest that serum leptin is associated with the presence of brain infarcts at baseline in patients with MCI and AD, however neither leptin nor adiponectin are associated with the development of cerebral infarcts." (PMID 38686200, 2024). "The aim of this study was to assess the effects of a patient’s body mass index (BMI) and leptin levels on the occurrence of DCI, DCI-related cerebral infarction, and clinical outcome." (PMID 33866464, 2021). "Multivariate longitudinal analysis showed that age was the only significant predictor of brain infarcts development at 15-year follow-up, while serum leptin and adiponectin levels did not play a role in this population." (PMID 38686200, 2024). "Multivariate logistic regression analysis at baseline for the presence of brain infarcts showed a predictive value for leptin but not for adiponectin." (PMID 38686200, 2024). "To evaluate the influence of leptin and adiponectin on the presence of brain infarcts in AD and MCI subjects, we built two multivariable fractional polynomial logistic regression models for the presence or absence of silent brain infarct at baseline." (PMID 38686200, 2024).
brain inflammation (4 papers, 2015 to 2025). "Activated macrophage infiltration, polarization of macrophages to a more inflammatory type (M1), and increased levels of pro-inflammatory cytokines are related to brain inflammation, which induces leptin resistance in the brain." (PMID 31739649, 2019). "In old rats, brain inflammation induced by LPS has been associated with increased peripheral inflammatory markers and hyperleptinemia, while treatment with anti-leptin serum partially reverses brain inflammation, highlighting the crucial role of leptin as a mediator of brain inflammation in aging." (PMID 29156608, 2017).
Central hypothyroidism (4 papers, 2009 to 2021). A type of hypothyroidism due to an insufficient stimulation of an otherwise normal thyroid gland. "The diminished leptin effect on TRH stimulation is also evident in LEPR deficiency where central hypothyroidism is observed in 13% of cases." (PMID 34177811, 2021). "In states of leptin-deficiency, the circadian rhythm of TSH is altered, leading to central hypothyroidism in animal models." (PMID 19889232, 2009).
colon adenoma (4 papers, 2014 to 2025). An adenoma that arises from the colon. "We evaluated mediating effects of adiponectin and leptin on the association of abdominal adiposity and colon adenoma separately according to race using mediational pathway analysis." (PMID 25197277, 2014). "The present study explored serum adiponectin, leptin, IGF-1, and TNF-α association with colon adenoma." (PMID 29593647, 2018).
congenital generalized lipodystrophy (4 papers, 2021 to 2026). An extremely rare autosomal recessive condition, characterized by an extreme scarcity of fat in the subcutaneous tissues. "While leptin has been approved for the treatment of metabolic disorders in patients with congenital generalized lipodystrophy (CGL), the effects of chronic leptin deficiency and the treatment on vascular contractility remain unknown." (PMID 34638939, 2021). "Congenital generalized lipodystrophy (CGL) is a rare disorder marked by near-total loss of adipose tissue and severe metabolic disturbances due to leptin deficiency and the inability to store nutrients in adipose tissue effectively." (PMID 42222073, 2026). "Patients with congenital generalized lipodystrophy (CGL) have very low levels of leptin and are described as having a voracious appetite." (PMID 33411809, 2021). "Congenital generalized lipodystrophy (CGL) is a rare disorder characterized by near-complete absence of adipose tissue, resulting in very low or undetectable circulating leptin levels." (PMID 41341138, 2025).
coronary artery calcification (4 papers, 2014 to 2025). Calcification of the coronary artery, used as a measure of coronary atherosclerosis, a risk factor for myocardial infarction. "Moreover, in Caucasians, serum leptin has been independently associated with coronary artery calcification after adjustment for age, sex, family history of CVD, DM status, exercise, and major cardiometabolic medications." (PMID 28743977, 2017). "Elevated plasma leptin levels in Type 2 diabetic and obese patients directly correlate with the degree of coronary artery calcification." (PMID 34064112, 2021). "For example, serum leptin was positively associated with higher coronary artery calcification in asymptomatic participants without DM5." (PMID 28743977, 2017).